IL6 (interleukin 6)
Diseases named in the same sentence as IL6 in open-access papers (continued):
Sharing a sentence is not in itself a finding about the gene and the disease.
Obesity (continued). "Statistically, the concentrations of GROα, IL-2, IL-4, IL-6, IL-17A, IL-22, IL-23, and MCP-3 were significantly higher in males with obesity compared to the females with obesity, while the concentrations of IL-5, IL-10, IL-18, MCP-1, and MIP2α trended higher (p ≤ 0.1)." (PMID 41488663, 2025). "In obesity, the proliferation of adipose tissue accommodates elevated levels of proinflammatory immune cells (M1 macrophages, T cells) that release cytokines (TNF-α, IL-6, and IL-1β)." (PMID 40718355, 2025). "IL6, as a classic pro-inflammatory cytokine, plays a dual role in BPA-induced obesity." (PMID 41226680, 2025). "Males with obesity also had a higher trend (p ≤ 0.1) for the concentration of IL-6 compared to non-obese males." (PMID 41488663, 2025). "We determined the circulating concentrations of adiponectin, leptin, resistin, TNFα, and IL-6 in participants with obesity and type 2 diabetes with and without obesity, and compared them to those of the control group." (PMID 40095937, 2025). "ENOblock inhibited the pathology of diet-induced obesity by acting as a transcriptional repressor of master regulators of lipid homeostasis (Srebp-1a and Srebp-1c), gluconeogenesis (Pck-1), and inflammation (TNF-α and IL-6)." (PMID 40943261, 2025). "In obesity, elevated levels of TNF-α and IL-6 indicate low-grade chronic inflammation." (PMID 41010046, 2025). "Notably, TRPV4 knockout mice exhibited elevated thermogenic gene expression in adipose tissue, attenuated HFD-induced obesity, and decreased levels of inflammatory cytokines such as TNF-α and IL-6." (PMID 40076916, 2025). "Similarly, omentin—secreted by visceral fat stromal cells—demonstrates anti-inflammatory properties, with inverse correlations reported between its circulating levels and markers such as CRP, IL-6, and TNF-α in individuals with obesity." (PMID 40868054, 2025). "Studies have shown that OSA patients demonstrate higher levels of inflammatory factors (CRP, fibrinogen, TNF-α, IL-6), regardless of obesity status." (PMID 40428013, 2025). "Adipose tissue, particularly in the context of obesity, undergoes pathological expansion characterized by adipocyte hypertrophy, hypoxia, and stress responses that trigger the production of pro-inflammatory cytokines including TNF-α, IL-6, and IL-1β." (PMID 40551741, 2025). "In obesity, adipose tissue becomes inflamed and dysfunctional, releasing excess free fatty acids (FFAs) and pro-inflammatory adipokines, including tumor necrosis factor α (TNF-α) and interleukin 6 (IL-6)." (PMID 40218971, 2025). "Leptin is involved in the upregulation of IL-6 and TNF-α, contributing to obesity-related low-grade inflammation, promoting vascular dysfunction by contributing to hypertension, angiogenesis, and atherosclerosis, and interacting with insulin, affecting glucose and lipid metabolism." (PMID 40724644, 2025). "In this respect, the increased secretion of IL-6 and TNF-α in chronic inflammation-related obesity may activate the HPA axis and promote depressive behaviour." (PMID 41375608, 2025). "Obesity manifests as a chronic low-grade inflammation characterized by increased circulating levels of inflammatory factors such as tumor necrosis factor-α (TNF-α), interferon-γ (IFN-γ), interleukin-1β (IL-1β), and interleukin-6 (IL-6)." (PMID 40519937, 2025). "Adipose tissue, especially in the context of obesity, acts as an immunologically active organ, releasing pro-inflammatory cytokines such as TNF-α, IL-6, and IL-1β, which impair insulin signaling, promote endothelial dysfunction, and contribute to vascular inflammation." (PMID 40870891, 2025). "In terms of inflammatory response, obesity is often accompanied by a state of systemic inflammation, characterized by increased levels of pro‐inflammatory cytokines such as TNF‐α, IL‐6, and IFN‐γ, alongside a decrease in anti‐inflammatory cytokines such as IL‐4 and IL‐10." (PMID 39968210, 2025).
Obesity (continued). "A similar trend was observed in this study, where obesity reduced the activities of oxidative stress enzymes SOD, CAT, and GSH‐PX, while increasing oxidative damage markers such as MDA and GSH, as well as inflammatory factors IL‐6 and TNF‐α." (PMID 40260060, 2025). "Pairwise comparisons showed children with PWS (p = 0.047) and with obesity (p = 0.022) had a greater IL‐6 AUC compared to children without obesity." (PMID 40243109, 2025). "Despite the well-known connection between obesity and chronic subclinical inflammation, we did not observe a significant reduction in the studied inflammatory markers (ferritin, IL-6, TNF- α resistin, PAI-1) following the treatment with submaximal GLP-1 RA." (PMID 41011232, 2025). "In the state of obesity, adipose tissue serves not only as an energy reservoir but also as an endocrine organ that releases a large amount of proinflammatory factors, including an increased level of TNF‐α, which further promotes the release of IL‐6." (PMID 40599237, 2025). "Likewise, in females with obesity, vaccinated mice had significantly lower levels of eotaxin, GM-CSF, GRO-α, IL-1β, IL-2, IL-5, IL-6, IL-12p70, IL-17A, IL-18, IP-10, MCP-1, MCP-3, MIP-1α, MIP-1β, MIP-2α, and TNF-α compared to unvaccinated controls." (PMID 41488663, 2025). "The excess adiposity exhibited by children with PWS and those without PWS but with non‐syndromic obesity likely is related to the greater overall concentrations of IL‐6." (PMID 40243109, 2025). "In obesity, STAT3 is chronically stimulated due to elevated levels of IL-6 and leptin." (PMID 41515969, 2025). "Muscle-derived IL-6 can inhibit the production of inflammatory cytokines such as TNF-α and IL-1β, while promoting secretion of anti-inflammatory cytokines like interleukin-10 (IL-10), thereby improving inflammatory profile in patients with sarcopenic obesity." (PMID 41141350, 2025). "Moreover, advanced chemoattraction and migration of monocytes, their subsequent polarization into inflammatory macrophage phenotypes, and secretion of IL‐1ꞵ, IL‐6, and TNF‐α are also extensively observed to occur via LTB4 in obesity and from adipose tissue." (PMID 39943721, 2025). "Individuals with obesity were also classified as having high inflammation if their circulating levels of IL-6 and CRP were higher than the average in the lean, healthy controls (5.4 pg/mL for IL-6 and 0.67 mg/dL for CRP)." (PMID 40548377, 2025). "In contrast to TNF-α, plasma rather than adipose IL-6 demonstrated the strongest relationship with obesity and insulin resistance." (PMID 41155523, 2025). "Alongside these, inflammatory cytokines such as tumor necrosis factor-alpha (TNF-α), interleukin-6 (IL-6), and C-reactive protein (CRP) are significantly influenced by changes in adipose tissue dynamics and play a central role in the development of obesity-related complications." (PMID 40710568, 2025). "In addition, our team has studied the inflammation in taste bud cells and demonstrated that diet-induced obesity or LPS-triggered inflammation increased TNF-α, IL-1β, and IL-6 expression, both at mRNA and protein levels, in taste bud cells." (PMID 40284173, 2025). "Additionally, semaglutide demonstrated neuroprotective benefits to the CNS leading to enhancement to cell survival, decreased M1-like microglia numbers, and reduced interleukin-6 and TNF-α levels in different brain areas in obesity." (PMID 40240584, 2025). "However, obesity‐driven overproduction of pro‐inflammatory cytokines, such as TNF‐α and IL‐6, suppresses ADPN, further amplifying inflammation and metabolic dysregulation." (PMID 40452002, 2025). "However, adiponectin serum levels decrease in obesity due to adiponectin transcription and translation suppression in an adipocyte cell line by TNF, IL-6, and other pro-inflammatory mediators." (PMID 41227271, 2025).
Obesity (continued). "A notable proportion of network hubs—including FXR, GPBAR1, IL6, and TNF—were shared across multiple disease pathways, emphasizing the relevance of probiotic metabolites in modulating conditions such as type 2 diabetes, obesity, NAFLD, and IBD." (PMID 40612394, 2025). "Obesity-induced inflammation tends to exacerbate metabolic disorders, and we also found improvements in inflammatory markers, manifested as the decrease of inflammatory factors TNF-α, IL-1α, IL-6, and chemokine Eotaxin elicited by nicotine." (PMID 41488304, 2025). "Obesity is characterized by an expansion of adipose tissue that becomes infiltrated by immune cells, notably macrophages, which secrete proinflammatory cytokines such as tumor necrosis factor-α (TNF-α) and interleukin-6 (IL-6)." (PMID 40868103, 2025). "For instance, in the context of obesity-driven HCC, the pro-inflammatory cytokine IL-6, in concert with androgen receptor signaling, can induce the expression of the cell cycle-related kinase (CCRK), which in turn establishes a positive feedback loop to drive mTORC1 activation." (PMID 41208895, 2025). "The expression and secretion of many adipokines, such as leptin, resistin, tumor necrosis factor-α (TNF-α), interleukin-6 (IL-6), C-C motif chemokine ligand 2 (CCL2), CXC motif chemokine ligand 5 (CXCL5), and angiopoietin-like 2, are up-regulated in AT during obesity." (PMID 40076419, 2025). "This review examines macrophage ontogeny, polarization, and functional heterogeneity in ORBC, highlighting how obesity-induced cytokines (e.g. TNF-α, IL-6), reactive oxygen species, and metabolic reprogramming collectively reshape the TME to foster tumor initiation, progression, and metastasis." (PMID 41310829, 2025). "In Canadian survivors of childhood acute lymphoblastic leukemia (n = 241; including 85 under 18 years), stratified models by obesity status showed higher IL-6 at greater UPF intake in both obese and non-obese participants." (PMID 41010537, 2025). "From a biological perspective, obesity-related chronic inflammation may accelerate atherosclerosis by promoting systemic inflammatory responses (e.g., CRP, IL-6), increasing plaque vulnerability and thereby compounding stroke risk." (PMID 41041669, 2025). "Conversely, IL-6 did not display a significant trend with BMI (R2 = 0.014), reinforcing its role as an obesity-independent inflammatory marker." (PMID 41523554, 2025). "Pro-inflammatory cytokines (IL-1β, IL-6, TNF) surge while IL-10 drops in obesity." (PMID 41562075, 2025). "In adults, a RE protocol induced increased IL‐6 immediately post‐exercise in young men with and without obesity and in young men with PWS." (PMID 40243109, 2025). "TNF-α, interleukin-6 (IL-6) and plasminogen activator inhibitor-1 (PAI-1) may regulate BP in obesity." (PMID 40761303, 2025). "Obesity induces a state of chronic low-grade inflammation characterized by elevated adipokines (e.g., leptin) and proinflammatory cytokines (e.g., TNF-α and IL-6), which promote airway hyperreactivity, increase mucosal permeability, and amplify IgE-mediated responses to occupational allergens." (PMID 41154935, 2025). "In detail, it is proved that in obesity, chronic low-grade inflammation is present since adipose tissue produces pro-inflammatory cytokines (e.g., TNF-α, IL-6), chemokines (monocyte chemoattractant protein (MCP1/CCL2), and pro-inflammatory fatty acids, leading to systemic inflammation." (PMID 40566087, 2025). "Notably, diabetes and obesity are always accompanied by chronic low‐grade inflammation, but JTTZF significantly reduced pro‐inflammatory cytokines (IL‐1β, TNF‐α and IL‐6) in diabetic mouse livers." (PMID 41250907, 2025). "Specifically, cortisol levels were found to be higher in all the HAdV-36-positive subjects, while individuals with normal weight, overweight, and obesity had significantly higher levels of IL-6, compared to the subjects negative for HAdV-36." (PMID 40136420, 2025).
Obesity (continued). "In patients with obesity, insulin resistance can be triggered by WAT inflammation, as WAT inflammation leads to the release of pro-inflammatory cytokines, such as TNFα, IL-1β, IL-6, that inhibit insulin signaling and impaired glucose uptake." (PMID 40456448, 2025). "At the molecular level, obesity is characterized by excessive release of free fatty acids, which promotes lipotoxicity, oxidative stress, and the activation of pro-inflammatory cytokines such as TNF-α and IL-6, contributing to insulin resistance." (PMID 41011571, 2025). "However, obesity can contribute to IR over time, further increasing inflammatory markers such as TNF-α, IL-6, IL-1β, IL-18, and MCP-1." (PMID 40218960, 2025). "Some studies suggest that a lower n-6:n-3 ratio may improve metabolic parameters in adolescents with obesity and fatty liver disease, enhance glucose and lipid metabolism in T2DM, and decrease serum levels of TNF-α, IL-1β, IL-6, and MCP-1." (PMID 40573106, 2025). "In obesity, pro-inflammatory M1 macrophages infiltrate adipose tissue, and in conjunction with hypertrophic adipocytes, they secrete cytokines such as tumour necrosis factor-alpha (TNF-α), interleukin-6 (IL-6), and monocyte chemoattractant protein-1 (MCP-1)." (PMID 41010046, 2025). "Carefully selected participants—non-smokers, without obesity, somatic or metabolic comorbidities—enabled the minimisation of known modulators of peripheral IL-6 levels." (PMID 41008291, 2025). "In individuals with obesity, adipose tissue becomes a source of inflammation, producing higher levels of proinflammatory markers like tumor necrosis factor-alpha (TNF-α), interleukin-6 (IL-6), and monocyte chemotactic protein-1." (PMID 40722684, 2025). "In obesity, an imbalance in adipokine production results in elevated pro-inflammatory mediators (e.g., tumor necrosis factor alpha (TNF-α) and interleukin-6 (IL-6)) and decreased cardioprotective adipokines, such as adiponectin, fostering systemic inflammation and apoptosis." (PMID 40688840, 2025). "Similarly, plasma levels of IL-6 and TNF-α are increased in obesity and other pathological conditions, with high levels of these cytokines associated with a greater risk of CVDs." (PMID 40642747, 2025). "Furthermore, obesity triggers chronic low‐grade inflammation, with adipose tissue producing pro‐inflammatory mediators such as TNF‐α and IL‐6." (PMID 40661797, 2025). "Obesity-related cytokines (such as TNF-α, IL-6) may inhibit the HPG axis and impair Leydig cell function, further decreasing testosterone secretion." (PMID 40162320, 2025). "Thus, we selected IL-6 as the factor connecting inflammation to the growth of colorectal cancer and RBP4 as the link between obesity and tumorigenesis." (PMID 41007818, 2025). "This interplay is recognized as a key driver of metaflammation, as ATMs actively contribute to systemic low-grade inflammation in obesity through the secretion of pro-inflammatory cytokines such as TNF-α, IL-6, and IL-1β, which are major instigators of the insulin resistance phenomenon." (PMID 41226484, 2025). "In obesity, vWAT undergoes pathological expansion and becomes a significant source of inflammatory cytokines, including tumor necrosis factor-alpha (TNF-α) and interleukin-6 (IL-6), exacerbating systemic insulin resistance." (PMID 40699742, 2025). "Obesity induces a chronic low-grade systemic inflammatory state, wherein adipose tissue dysfunction leads to abnormal secretion of adipokines (e.g., leptin and adiponectin) and pro-inflammatory cytokines such as TNF-α, IL-6, and IL-1β." (PMID 41305576, 2025). "CR or CREX interventions, as opposed to EX alone, have been shown to decrease IL-6 concentrations in people with overweight or obesity, independent of body weight changes." (PMID 39929932, 2025).
Obesity (continued). "Adipose tissue plays a crucial role in immune modulation, with dysfunctional adipose tissue in conditions like obesity or lipodystrophy releasing pro‐inflammatory cytokines (e.g., TNF‐α, IL‐6), which alter hepatic inflammation, a key factor in liver regeneration." (PMID 39980067, 2025). "Obesity drives Th2-type (eosinophilic) or Th17-type (neutrophilic) inflammation in asthma through an imbalance between pro-inflammatory factors (leptin, TNF-α, IL-6) and anti-inflammatory factors (adiponectin) secreted by adipose tissue." (PMID 41244254, 2025). "This suggests that monitoring the secretion levels of IL-6 and MCP-1 could be used to assess liver prognosis in HIV + participants considering comorbid conditions such as obesity." (PMID 41219858, 2025). "Obesity-related asthma is associated with a Th1 immune response (involving TNF-α, IFN-γ, IL-6, and IL-8) rather than a Th2 response (which involved IL-4, IL-5, IL-10, and IL-13)." (PMID 40083433, 2025). "Notably, IL-1β, IL-6, and TNF-α are major proinflammatory cytokines known to be involved in obesity-induced inflammation." (PMID 40118456, 2025). "Moreover, obesity is related to elevated levels of circulating pro‐inflammatory markers, such as TNF‐α and IL‐6." (PMID 40620232, 2025). "Circulating levels of inflammatory mediators, such as C-reactive protein (CRP) and its inducer interleukin (IL)-6, are increased in individuals with obesity compared to those without obesity." (PMID 40565915, 2025). "Therefore, the aim of this secondary analysis was to compare the effects of TRE versus CR on key inflammatory markers (TNF-alpha, IL-6, and CRP) in adults with obesity over 12 months." (PMID 40218888, 2025). "Additionally, obesity promotes chronic inflammation, with adipose tissue acting as a source of pro-inflammatory cytokines such as TNF-α, IL-6, and IL-1β, which exacerbate lipid deposition in the liver." (PMID 40551780, 2025). "Similarly to IL-6, TNF-α is a synonym of inflammation and has even been considered the link between insulin resistance and obesity." (PMID 41515940, 2025). "A significant positive correlation was also observed between baseline DII and IL-6 levels in the lipedema group, but not in the overweight/obesity group." (PMID 41010539, 2025). "Children with excess body fat due to PWS or due to non‐syndromic obesity exhibited greater IL‐6 concentrations than those without excess body fat." (PMID 40243109, 2025). "Obesity is also believed to affect treatment response in PsA and AxSpA by inducing a chronic low-grade inflammatory state through inflammatory mediators such as TNF-alpha and interleukin-6." (PMID 39150473, 2025). "This review examines the major mechanisms between obesity and AD, which focus on the effect on skin and gut microbiota, immune responses mediated by the toll like receptor (TLR) signaling pathway, and changes in cytokine levels (TNF-a, IL-6, IL-4, and IL13)." (PMID 39564133, 2024). "Two kidney-focused clinical trials testing either suppression of IL-6 with siltuximab (NCT02641522) in T1D patients or inhibition of IL-6R with tocilizumab in patients suffering from T2D and obesity (NCT01073826) were conducted but the results and conclusions are pending." (PMID 39723211, 2024). "Obesity is characterized by an excessive accumulation of adipose tissue, which secretes a range of pro-inflammatory cytokines such as tumor necrosis factor-alpha (TNF-α) and interleukin-6 (IL-6)." (PMID 39588433, 2024). "Obesity has a significant inflammatory component and overweight individuals have increased serum levels of inflammatory cytokines such as tumor necrosis factor alpha (TNF-α), CRP and interleukins (IL-6, IL-18)." (PMID 38330593, 2024). "In obesity and diabetes their mechanisms of action mostly rely on decreasing TNF-α and IL-6 levels." (PMID 38504163, 2024).